TUG1 (taurine up-regulated 1)
Diseases named in the same sentence as TUG1 in open-access papers (continued):
Sharing a sentence is not in itself a finding about the gene and the disease.
glioma (continued). "However, TUG1 as a tumor suppressor in some other tumors including non-small cell lung cancer (NSCLC), glioma, and urothelial carcinoma (UC), up-regulated TUG1 inhibit cell proliferation and reduce tumorigenicity." (PMID 29029461, 2017). "As a tumor suppressor in glioma, lncRNA TUG1 could activate caspase-3 and caspase-9 dependent pathways and suppress Bcl-2 dependent anti-apoptosis pathway." (PMID 28548946, 2017). "However, in patients with non-small cell lung cancer (NSCLC), urothelial carcinoma (UC) or glioma, the increased TUG1 expression is correlated with favorable survival." (PMID 29029461, 2017). "Besides, the expression level of TUG1 in high-grade glioma group was up-regulated compared with that in the low-grade glioma group (P < 0.01)." (PMID 26078353, 2015). "Besides, the relative mean optical densities of TUG1 in high-grade glioma group was up-regulated compared with that in the low-grade glioma group (P < 0.05)." (PMID 26078353, 2015). "Moreover, the TUG1 lncRNA was found to sponge miR-145, which is a reported tumor suppressor that helps regulate SOX2 and MYC mRNA levels and thus upregulates the abundance of these key stemness-associated TFs in glioma." (PMID 37444543, 2023). "Therefore, depleting TUG1 in glioma cells might facilitate a microenvironment detrimental for tumor growth while beneficial for drug delivery." (PMID 30116729, 2018). "Thus, there may be potential role of TUG1 in anti-glioma therapy, and BTB function may represent a useful therapeutic intervention strategy in the future." (PMID 28293170, 2017). "However, TUG1 was downregulated in non-small cell lung cancer and glioma." (PMID 28376901, 2017). "However, TUG1 has been found to be down-regulated in human glioma, indicating that TUG1 is tissue-specific and may function as oncogene or tumor suppressor in different cancer." (PMID 27421138, 2016). "Based on this model, we revealed for the first time that the expression of TUG1 was significantly up-regulated in glioma co-cultured endothelial cells compared with normal astrocytes co-cultured endothelial cells, suggesting that TUG1 might be involved in the regulation of BTB function." (PMID 26078353, 2015). "Modulating TUG1 expression or inhibiting FTH1 can augment the antiglioma effects of DHA, presenting a promising strategy to enhance DHA’s effectiveness against glioma." (PMID 39267831, 2024). "Despite the fact that many lncRNAs (e.g., TUG1 and MIR22HG) have been revealed to be markedly dysregulated in gliomas, the functions and mechanisms of lncRNAs in gliomas have not yet been explored thoroughly." (PMID 37100464, 2023). "The silencing of TUG1 or overexpression of EZH2 enhances CSC-like properties and resistance to temozolomide in A172 glioma cells." (PMID 37958880, 2023). "In fact, low expression of TUG1 lncRNA and high expression of Enhancer of zeste homolog 2 (EZH2) was observed in glioma cells." (PMID 37958880, 2023). "Downregulated expression of TUG1 and upregulated expression of MAZ were confirmed in DHA treated glioma cells." (PMID 36164395, 2022). "Downregulated expression of TUG1 and upregulated expression of MAZ were identified in DHA treated glioma cells." (PMID 36164395, 2022). "In DHA-treated glioma cells, LPO and ROS were significantly increased combined with TUG1 overexpression." (PMID 36164395, 2022). "Previous studies have shown that some lncRNAs, such as TUG1, UCA1, and AFAP1-AS1, regulated the expression of miR-145 by a sponging mechanism in glioma stem cells (GSCs), nasopharyngeal carcinoma (NPC) cell lines, and OSCC cell lines, respectively." (PMID 34946098, 2021). "The expression levels of TUG1, miR-144 and HSF2 in human glioma vascular endothelial cells and normal brain vascular endothelial cells were detected by quantitative real-time PCR." (PMID 26078353, 2015).
glioma (continued). "Studies have shown that TUG1 and MEG3 expression levels are reduced in human glioma tissues, with TUG1 promoting cell apoptosis and suppressing proliferation, migration, and invasion, while GAS5 was identified as a suppressor that enhances glioma therapy efficacy by directly targeting miR-222." (PMID 40004468, 2025). "Indeed, connections between TUG1 and either NOTCH1 or PD-L1 have already been described in the literature for glioma and hepatocellular carcinoma, respectively." (PMID 40407592, 2025). "Overexpression of TUG1 or inhibition of FTH1 expression enhances the antiglioma effect of DHA in vitro and in vivo, providing a promising method to enhance the antitumor effect of DHA in glioma." (PMID 36164395, 2022). "Finally, we observed the effects of TUG1 overexpression alone, MAZ overexpression alone, and both TUG1 and MAZ overexpression on cytotoxicity of DHA in glioma cells." (PMID 36164395, 2022). "Meanwhile, in some types of breast cancer, non-small-cell lung cancer, and glioma, TUG1 was expressed at a low level when compared with noncancerous tissues and acts as a tumor suppressor." (PMID 33747256, 2021). "lncRNA TUG1 affected proliferation by directly regulation, internal pathways mediated by caspase-3 and-9, anti-apoptotic pathways mediated by Bcl-2, or miR-26a sponging PTEN in glioma." (PMID 34039257, 2021). "However, TUG1 was found to be downregulated and acted as a tumor suppressing gene in some types of breast cancer, NSCLC, and glioma." (PMID 33747256, 2021). "The fact that the TUG1 sequences responsible for interaction between TUG1, PRC2, and YY1 have been identified and seem well conserved between humans and mice, marks this transcript as a therapeutic candidate of self-renewal in Glioma Stem Cells (GSC)." (PMID 31658672, 2019). "In addition, after treatment with DNA damaging reagents, such as doxorubicin and resveratrol, specific candidate lncRNAs (MEG3, ST7OT1, TUG1, BC200 and MIR155HG) are detected in human glioma cell lines (U251 and U87)." (PMID 28293170, 2017). "Interestingly, previous studies have shown that TUG1 were up-regulated in BRC, CRC, OC, SCLC, OSA, GC, ESCC, ccRCC, BC and MIBC, and function as an oncogene, while TUG1 were down-regulated in NSCLC, glioma as well as UC, and function as a tumor suppressor." (PMID 29029461, 2017). "In addition, some lncRNAs, such as lncRNA CASC2, TUG1, TSLC1-AS1, have been characterized as tumor suppressors in glioma." (PMID 27104549, 2016). "TUG1 overexpression or inhibition of FTH1 expression could enhance the antiglioma effect of DHA in vitro and in vivo, providing a promising strategy to enhance the antitumor effect of DHA in glioma." (PMID 36164395, 2022). "Furthermore, we developed new antisense oligonucleotides (ASO) targeting TUG1 coupled with a potent drug delivery system (DDS), which can be used intravenously to provide efficient and selective delivery to glioma cells at sufficient concentrations to acquire antitumour effects." (PMID 27922002, 2016). "For example, TUG1-hsa-miR-26a-PTEN, which is a competing triplet that involved in the BRCA tumor state, has been demonstrated that TUG1 could serve as a miR-26a sponge and then contribute to the up-regulation of PTEN in human glioma cells." (PMID 27580177, 2016).
bladder cancer (49 papers, 2014 to 2025). "For example, in bladder cancer, lncRNAs such as TUG1 and SNHG1 have been implicated in modulating autophagy and contributing to therapy resistance through interactions with key signaling pathways like PI3K/Akt/mTOR and PP2A catalytic subunit, respectively." (PMID 39512820, 2024). "The expression of lncRNA TUG1 was down-regulated and used as a diagnostic marker in bladder cancer tissues." (PMID 34039257, 2021). "In the present study, we aimed to investigate the effect of TUG1 on the radiosensitivity of bladder cancer cells and its underlying molecular mechanisms." (PMID 28376901, 2017). "Over-expression of TUG1 associated with significantly unfavorable survival for bladder cancer (HR=2.67, 95% CI: 1.47–4.87, P = 0.001)." (PMID 29029461, 2017). "In the present study, we explored function and underlying mechanisms of lncRNA TUG1 in the radiosensitivity of bladder cancer." (PMID 28376901, 2017). "In bladder cancer, TUG1 decreased the expression of miR-145 and caused upregulation of ZEB2, miR-145 target, promoting EMT, and increasing the metastatic proneness of bladder cancer cells." (PMID 29147648, 2017). "Interestingly, in the context of the present study, in bladder cancer cells, TUG1 expression was associated with increased proliferation, migration, and invasion." (PMID 33059750, 2020). "In addition, TUG1 is another lncRNA that was significantly increased in bladder cancer and was associated with reduced overall survival of bladder cancer patients." (PMID 29719633, 2018). "Aberrant expression of lncRNA Taurine-upregulated gene 1 (TUG1) has been found to be involved in the development of bladder cancer, however, its function and underlying mechanism in the radioresistance of bladder cancer remains unclear." (PMID 28376901, 2017). "Moreover, radiation increased TUG1 expression, which implied that TUG1 may be associated with the radioresistance in bladder cancer." (PMID 28376901, 2017). "In bladder cancer cells, TUG1 possesses direct miRNA interaction capability and can regulate the EZH2 expression level." (PMID 38256203, 2024). "Accordingly, the downregulation of TUG1 leads to higher cisplatin sensitivity of bladder cancer cells." (PMID 38256203, 2024). "Accordingly, the knockdown of TUG1 in bladder cancer cells lowers EZH2 expression, thereby reducing miR-194-5p methylation and inducing its expression." (PMID 38256203, 2024). "The knockdown of either ZEB2 or TUG1 inhibited cell proliferation and induced apoptosis in bladder cancer." (PMID 37627900, 2023). "Increased expression of lncRNA TUG1 (Taurine Upregulated Gene 1) is seen in different types of cancers such as bladder carcinoma, stomach cancer, and bone sarcoma, while its decreased expression is seen in non-small cell lung cancer (NSCLC)." (PMID 36359888, 2022). "In bladder cancer cells, lncRNA TUG1 increases ZEB2 expression by inhibiting miR‐142 and inhibits the Wnt/β‐catenin pathway to promote cell proliferation and inhibit apoptosis." (PMID 35421276, 2022). "TUG1 played important role in the development or progression of hepatocellular carcinoma, stomach adenocarcinoma and Bladder Cancer." (PMID 36567977, 2022). "The down-regulation of lncRNA TUG1 enhanced the radiosensitivity of bladder cancer cells by inhibiting the expression of high mobility group box-1 protein (HMGB1)." (PMID 34039257, 2021). "Another 4 studies included 256 bladder cancer patients, 3 studies from China and 1 from the Czech Republic, with the results suggesting that patients with higher TUG1 expression have a lower survival rate." (PMID 33747256, 2021). "The upregulation of lncRNA TUG1 promoted the proliferation, migration, and invasion of bladder cancer cells by inhibiting miR-29c." (PMID 34039257, 2021). "In accordance, lncRNA TUG1 can regulate the growth, proliferation, and invasion of oral squamous cell carcinoma, bladder cancer, and prostate cancer through the Wnt/β-catenin signalling pathway." (PMID 34039257, 2021).
bladder cancer (continued). "LncRNA TUG1, on the other hand, promotes cisplatin resistance through the epigenetic regulation of miR-194-5p in bladder cancer." (PMID 34497804, 2021). "Recently, it has been reported that TUG1 silencing inhibits the proliferation and leads to apoptosis of bladder cancer cells by inhibiting Wnt/B-catenin pathway." (PMID 34026626, 2021). "In esophageal squamous cell cancer and bladder cancer, lncRNA TUG1 was involved in the occurrence of cisplatin resistance, and the development of azithromycin resistance in urothelial cancer of the bladder and acute myelogenous leukemia." (PMID 34039257, 2021). "lncRNA TUG1 promoted the proliferation of cancers, such as oral squamous cell cancer, bladder cancer, and prostate cancer." (PMID 34039257, 2021). "A previous study revealed that taurine-upregulated gene 1 (TUG1) is required for the cell metastasis of human bladder cancer." (PMID 33292252, 2020). "It was reported that TUG1 promoted radioresistance of bladder cancer, which agrees with our findings." (PMID 28376901, 2017). "Collectively, these data demonstrated that TUG1 knockdown enhances radiosensitivity of bladder cancer cells SW780 and BIU87." (PMID 28376901, 2017). "In the present study, we found that TUG1 expression was increased in bladder cancer tissues and cell lines, which was consistent with the data of previous studies." (PMID 28376901, 2017). "All these findings demonstrate that TUG1 knockdown contributes to the increase of radiosensitivity of bladder cancer cells in vivo and in vitro." (PMID 28376901, 2017). "Our study declared that TUG1 expression was markedly upregulated in bladder cancer tissues and cell lines." (PMID 28376901, 2017). "In their study, TUG1 knockdown in NSCLC cell lines promoted cellular proliferation, whereas in T24 bladder cancer cells TUG1 overexpression increased cell invasion." (PMID 28430799, 2017). "Downregulation of TUG1 enhanced the radiosensitivity of bladder cancer cells via inhibiting HMGB1 expression." (PMID 28376901, 2017). "All these results illustrated that silencing of TUG1 inhibited the HMGB1 expression in bladder cancer cell lines." (PMID 28376901, 2017). "In consistent with our surmise, our findings reveal that IncRNA TUG1 knockdown enhances radiosensitivity of bladder cancer through suppressing HMGB1 expression." (PMID 28376901, 2017). "TUG1 was upregulated in bladder cancer tissues and cell lines, and promoted cancer cell invasion and radioresistance through inducing epithelial-to-mesenchymal transition (EMT)." (PMID 28376901, 2017). "Additionally, in bladder cancer, lncRNAs like TUG1 and SNHG1 have been shown to modulate autophagy through interactions with signaling pathways such as miR-145/ZEB2 and PP2A catalytic subunit, respectively." (PMID 39512820, 2024). "TUG1 promoted bladder cancer cell invasion and radiotherapy resistance by inducing EMT." (PMID 37627900, 2023). "The expression of TUG1 was found to be upregulated in bladder cancer tissues and cell lines." (PMID 37627900, 2023). "And TUG1 could regulate resistance and sensitivity of some cancers to chemotherapeutic drugs, such as bladder cancer, cervical cancer and EC." (PMID 35645836, 2022). "lncRNA TUG1 has been found to enhance radioresistance in bladder cancer via miR-145/ZEB2 axis." (PMID 35600868, 2022). "Although lncRNA TUG1 could reduce the radiosensitivity of bladder cancer, it could also enhance the radiosensitivity of esophageal cancer." (PMID 34039257, 2021). "Only lncRNA TUG1 contributes to radiosensitivity in bladder cancer." (PMID 34422802, 2021). "TUG1 is widely expressed in various tumors and exhibits high expression levels in nervous system tumors, colorectal cancer, hematological system tumors, and bladder cancer." (PMID 34660799, 2021). "The expression of lncRNA TUG1 was up-regulated in bladder cancer tissues and cell lines." (PMID 34039257, 2021).
bladder cancer (continued). "As the functionality of TUG1 in bladder cancer is still unknown, further studies are needed with regard to a possible tumor suppressive effect." (PMID 33235218, 2020). "UCA and TUG1 are both known to promote cell proliferation and tumorigenesis in bladder carcinomas." (PMID 31379598, 2019). "Considering that radiation treatment could enhance the TUG1 expression, we assumed that TUG1 may be related to the radiation resistance in bladder cancer." (PMID 28376901, 2017). "TUG1 acts as a potential regulator of radioresistance of bladder cancer, and it may represent a promising therapeutic target for bladder cancer patients." (PMID 28376901, 2017). "LncRNA TUG1 knockdown enhances radiosensitivity of bladder cancer by suppressing HMGB1 expression." (PMID 28376901, 2017). "However, the function and molecular mechanism of TUG1 in bladder cancer radioresistance is still largely undefined." (PMID 28376901, 2017). "Our findings suggest that TUG1 could be a promising therapeutic target for bladder cancer and combination treatment of TUG1 knockdown and radiation may be a better strategy for the patients with radioresistant bladder cancer." (PMID 28376901, 2017). "Furthermore, our findings suggest that TUG1 knockdown enhances radiosensitivity of bladder cancer cells in vivo and in vitro by suppressing the expression of HMGB1." (PMID 28376901, 2017). "In summary, TUG1 expression was upregulated in bladder cancer tissues and cell lines." (PMID 28376901, 2017). "Together, TUG1 depletion improved the radiosensitivity of bladder cancer cells in vivo." (PMID 28376901, 2017). "Furthermore, overexpression of HMGB1 reversed TUG1 knockdown-induced effect in bladder cancer cells." (PMID 28376901, 2017). "Moreover, TUG1 knockdown enhanced the radiosensitivity of bladder cancer cell lines, evidenced by the reduced cell viability, the increased cell apoptosis and the inhibited colony survival fractions." (PMID 28376901, 2017). "Additionally, along the miR-145/ZEB2 pathway, the lncRNA TUG1, which is significantly expressed at an elevated level in bladder cancer samples and cells, promotes epithelial-mesenchymal transition (EMT) and reduces the susceptibility of cancer cells to ionizing radiation." (PMID 39512820, 2024). "Results from in vitro studies demonstrated that knockdown of TUG1 by siRNA significantly decreased proliferation and migration of bladder cancer cells, implicating thereby that lncRNAs could also be envisioned as potential therapeutic targets for preventing cancer invasion and metastasis." (PMID 29719633, 2018). "In addition, the decreased invasiveness of bladder cancer cells induced by knocking down TUG1 could be rescued by inhibiting miR-14546." (PMID 29467441, 2018). "Additionally, knockdown of TUG1 was able to reduce lung metastasis of bladder cancer cells in vivo." (PMID 28430163, 2017). "Moreover, the level of TUG1 is positively related to HMGB1 expression in bladder cancer tissues." (PMID 28376901, 2017). "In addition, aberrant expression of TUG1 has been observed in bladder cancer cells." (PMID 28376901, 2017). "Therefore, we explored whether TUG1 regulated the radiosensitivity of bladder cancer through modulating HMGB1 expression." (PMID 28376901, 2017). "Urinary exosomes from 42 bladder cancer patients were collected and quantified for seven lncRNAs (UCA1, H19, MALAT1, TUG1, GAS5, RMRP, and LINC01517), showing increased expression of RMRP, UCA1, and MALAT1 in bladder cancer patients." (PMID 40075875, 2025). "In another study, both the mRNA and protein expression of TUG1 and ZEB2 were significantly increased in bladder cancer tissues as compared to normal bladder tissues." (PMID 37627900, 2023). "lncRNA TUG1 affected proliferation by miR-299-3p/VEGF pathway, ZEB2/miR-142/wnt/β-catenin pathway, microRNA496/wnt/β-catenin pathway in renal cell carcinoma, bladder cancer, prostate cancer, respectively." (PMID 34039257, 2021).